ARL9 (ARF like GTPase 9)
Tractability: Antibody: the Human Protein Atlas places it where antibodies can reach.
Gene: Protein-coding gene on chromosome 4 (56,505,209 to 56,524,959, forward strand). Ensembl gene ENSG00000196503.
Subcellular location (Human Protein Atlas): Plasma membrane; Centriolar satellite; Cytosol
Gene Ontology:
Molecular function: GTP binding; GTPase activity
Genetic constraint (gnomAD): Loss-of-function variants: 12 observed, 20.08 expected, observed/expected ratio (o/e) 0.6, 90% interval 0.38 to 0.97. The upper end of that interval is the gene's LOEUF score, 0.97, which puts it in group 4 of 6, group 1 being the genes least tolerant of losing a copy. Missense variants: 239 observed, 236.17 expected, observed/expected ratio (o/e) 1.01, 90% interval 0.91 to 1.13. Synonymous variants: 89 observed, 89.69 expected, observed/expected ratio (o/e) 0.99, 90% interval 0.83 to 1.18.
Homologues: Orthologues: macaque ARL9 (94% identical), dog ARL9 (74% identical), rat Arl9 (66% identical), chimpanzee ARL9 (66% identical), tropical clawed frog arl9 (42% identical), pig ARL9 (39% identical), mouse Arl9 (38% identical), zebrafish arl9 (37% identical). Paralogues in human: ARL10 (27% identical), ARF1 (22% identical), ARF3 (22% identical), ARF6 (22% identical), ARL4C (22% identical), SAR1A (22% identical), ARL2 (21% identical), ARF4 (20% identical), ARL1 (20% identical), ARL3 (20% identical), ARL4D (20% identical), SAR1B (20% identical), and 18 more.
Diseases named in the same sentence as ARL9 in open-access papers:
ARL9 is named in the same sentence as 5 diseases in open-access papers, as found by Europe PMC text mining. Sharing a sentence is not in itself a finding about the gene and the disease. The quoted sentences say what the papers report.
colon adenocarcinoma (1 paper, 2023). "The mRNA expression of ARL9 is upregulated in colon adenocarcinoma, and higher mRNA expression levels are associated with a poor prognosis." (PMID 36823542, 2023). "The present study explored the associations between ARL9 mRNA levels and the initiation, development and prognosis of colon adenocarcinoma." (PMID 36823542, 2023). "Age and the high mRNA expression of ARL9 were independent risk factors for a poor prognosis in patients with colon adenocarcinoma." (PMID 36823542, 2023). "In conclusion, ARL9 plays an important role in the occurrence and progression of colonic adenocarcinoma." (PMID 36823542, 2023). "The present study demonstrated that the mRNA expression levels of ARL9 were significantly upregulated in colon adenocarcinoma tissues in comparison to adjacent normal tissues." (PMID 36823542, 2023). "The expression of ARL9 is upregulated in colon adenocarcinoma tissues, and patients with high ARL9 expression levels have a poorer prognosis." (PMID 36823542, 2023). "The CCK8 assay confirmed that the knockdown of ARL9 reduced the proliferation capacity of colon adenocarcinoma cells." (PMID 36823542, 2023). "The expression levels of ARL9 mRNA in colon adenocarcinoma tissues were higher than those in adjacent normal tissues, and the differences were statistically significant (P < 0.05)." (PMID 36823542, 2023). "We investigated the differential expression of ARL9 between colon adenocarcinoma tissue and adjacent tissues through a bioinformatics analysis using The Cancer Genome Atlas (TCGA) database." (PMID 36823542, 2023). "The effect of the expression of ARL9 on the proliferation and migration of colon adenocarcinoma was analyzed by the CCK8 method and a cell scratch test, respectively." (PMID 36823542, 2023). "After knocking down ARL9, the proliferation and migration abilities of colon adenocarcinoma cells were decreased (P < 0.01)." (PMID 36823542, 2023). "The GSEA suggested that ARL9 may be able to upregulate cell adhesion, extracellular matrix receptor interactions, tumor-associated pathways, and downregulate the citrate cycle and tricarboxylic acid cycle pathway, which are involved in the development of colon adenocarcinoma." (PMID 36823542, 2023). "The mRNA expression of ARL9 in colon adenocarcinoma tissues was higher in comparison to the level in normal adjacent tissues (P < 0.05)." (PMID 36823542, 2023). "The knockdown of ARL9 reduces the proliferation and migration ability of colon adenocarcinoma cells." (PMID 36823542, 2023). "The 5-year survival rate of patients with high ARL9 mRNA expression levels in colon adenocarcinoma tissues was significantly lower than that of patients with low expression levels (P < 0.05); their 5-year survival rates were 51.4% and 72.2%, respectively." (PMID 36823542, 2023). "In this study, we aimed to explore the expression of ARL9 mRNA in colon adenocarcinoma, and its effect on the prognosis of patients with colon adenocarcinoma." (PMID 36823542, 2023). "The mRNA expression of ARL9 was lower in colon adenocarcinoma patients of ≥ 50 years of age in comparison to those aged of < 50 years of age (P < 0.05)." (PMID 36823542, 2023). "The aim was to investigate the functional mechanism of ARL9 in colon adenocarcinoma and provide a basis for the diagnosis, treatment and prognosis of colon adenocarcinoma." (PMID 36823542, 2023). "The 5-year survival rate of colon adenocarcinoma patients with high ARL9 mRNA expression levels was significantly lower than that of patients with low ARL9 mRNA expression levels (P < 0.05)." (PMID 36823542, 2023). "Knocking down ARL9 can reduce the proliferation and migration of colon adenocarcinoma cells." (PMID 36823542, 2023). "ARL9 mRNA can be used as a prognostic biomarker in patients with colon adenocarcinoma." (PMID 36823542, 2023). "ARL9 can act as an independent prognostic predictor in colonic adenocarcinoma." (PMID 36823542, 2023).
colon adenocarcinoma (continued). "Finally, we conducted a gene set enrichment analysis (GSEA) to explore the ARL9 signaling pathways involved in the development of colon adenocarcinoma." (PMID 36823542, 2023). "In the present study, we analyzed the differences in the mRNA expression of ARL9 in colon adenocarcinoma tissues and adjacent normal tissues in The Cancer Genome Atlas (TCGA) database and the correlation between the mRNA expression of ARL9 and patients' clinical information." (PMID 36823542, 2023). "Finally, using in vitro experiments, the present study confirmed that ARL9 knockdown in HCT116 cells (a colon adenocarcinoma cell line) reduced the cell proliferation and migration abilities." (PMID 36823542, 2023). "However, as a newly identified member of the ARF family, the clinical and prognostic significance of ARL9 in colon adenocarcinoma is unknown, and its function in colon adenocarcinoma has never been reported." (PMID 36823542, 2023). "Therefore, we suggest that the upregulation of ARL9 mRNA may be related to the development and prognosis of colon adenocarcinoma and may promote tumor progression through membrane transport-related links, while its correlation with colon adenocarcinoma metastasis requires further study." (PMID 36823542, 2023). "ARL9 is a newly identified member of the ARF family, and the clinical significance of ARL9 in colon adenocarcinoma is unknown." (PMID 36823542, 2023).
glioma (1 paper, 2021). A benign or malignant brain and spinal cord tumor that arises from glial cells (astrocytes, oligodendrocytes, ependymal cells). "In contrast to STEAP3, the roles of ARL9 and CMYA5 in glioma have rarely been reported and remain obscure." (PMID 35111661, 2021).
prostate carcinoma (1 paper, 2014). A carcinoma that arises from epithelial cells of the prostate gland. "The model was able to identify prostate cancer associated SNPs that either map to a cancer specific genes such as CRR9, TERT, ATP2B2, ARL9, and AGBL4 and/or with regulatory effects." (PMID 24651484, 2014).
tumor (2 papers, 2023). "Meanwhile, we also compared the correlation between different tumor stages, T stage, N stage, M stage and ARL9 mRNA levels." (PMID 36823542, 2023). "The ARL9 protein expression was reported as correlating with CD8 T-cells in the LGG tissue, indicating the role of ARL9 methylation in tumor immune infiltration." (PMID 36831683, 2023). "The mRNA expression of ARL9 was not related to sex, tumor stage, T stage, N stage, M stage, but to age." (PMID 36823542, 2023).
ARL9 also shares sentences with these, for which no sentence is quoted: cancer (2 papers).